NLRC5 (NLR family CARD domain containing 5)
Diseases named in the same sentence as NLRC5 in open-access papers (continued):
Sharing a sentence is not in itself a finding about the gene and the disease.
melanoma (continued). "Previous reports have shown that in melanoma, MHC I and NLRC5 expressions correlate with a positive response to ICIs." (PMID 38235131, 2023). "In this study, we compared NLRC5-SA and NLRC5-FL for their ability to induce MHC-I expression in mouse and human cancer cell lines, control B16-F10 melanoma and EL4 thymoma growth in syngeneic C157BL/6 mice and modulate in MHC-I-associated peptides (MAPs)." (PMID 37108368, 2023). "The elevated NLRC5 expression enhanced MHCI cell surface expression and inhibited melanoma growth more effectively." (PMID 37163421, 2023). "In addition, truncating mutation and splice mutations, but not missense mutations of NLRC5 could compromise the expression of downstream genes in melanoma." (PMID 34307322, 2021). "However, here we revealed that neither mutation load nor neo-antigen load, but NLRC5 expression could effectively predict the melanoma patients’ response to the immunotherapy." (PMID 34307322, 2021). "Next, we obtained the bulk sequencing data of NLRC5 and clinical datasheet from the TCGA SKCM (Skin Cutaneous Melanoma) dataset and analyzed its clinical significance in melanoma." (PMID 34307322, 2021). "In addition, mutation load and neo-antigen load appear independent of NLRC5 status in melanoma." (PMID 34307322, 2021). "NLRC5 gene expression strongly correlates with expression of MHC-I and APM components across multiple cancers including prostate, lung, melanoma, thyroid, breast, uterine and ovarian cancer." (PMID 34201655, 2021). "Correlation between NLRC5 expression and infiltrating level of immune cell estimated by “MCP-counter” in melanoma datasets." (PMID 34307322, 2021). "Based on our observations of the potential value of NLRC5 as a biomarker in the anti-CTLA4 treatment cohort, we were inspired to extend the analysis to melanoma patient cohorts treated with anti-PD1 therapy." (PMID 33547395, 2021). "The effects of NLRC5 correlate with its expression levels, which can be enhanced by type I and II interferon (IFN), as shown also for melanoma cells." (PMID 27437103, 2016). "Moreover, high MHC-I expression has been proposed as a predictor of ICB response, and high expression of MHC-I and other APP genes, including NLRC5 and TAP1, correlates with better survival in patients with melanoma, for whom ICB is a first-line therapy." (PMID 38973593, 2024). "Moreover, high MHC-I expression has been proposed as a predictor of ICB response 28–31, and high expression of MHC-I and other APP genes, including NLRC5 and TAP1, correlates with better survival in patients with melanoma, for whom ICB is a first-line therapy." (PMID 37066260, 2024). "Human OC cells expressing NLRC5 display a gene signature positively correlating with immune and IFN-related genes potentially featuring ongoing natural antitumoral immunity, as has been noted in melanoma and Tasmanian devil transmissible cancer cells." (PMID 38235131, 2023). "Melanoma tumors derived from patients responding to immunotherapy exhibited significantly higher expression of NLRC5 and MHC class I-related genes compared to non-responding patients." (PMID 33547395, 2021). "In particular, the biological function and clinical significance of NLRC5 in melanoma have not been well demonstrated yet." (PMID 34307322, 2021). "In contrast to NLRC5, PD-1, which also regulates immune response, is mainly expressed in T cells rather than in malignant melanoma cells." (PMID 34307322, 2021). "Furthermore, correlation analysis in six melanoma immunotherapy datasets showed a highly significant positive correlation between SPI1 and NLRC5 expression (R>0.69, p < 0.001)." (PMID 34307322, 2021). "According to the melanoma SCRS data, all mir-149 targets identified were expressed in lymphocytes, some of which were exclusively expressed in this cell type and include CD96, CD48, SLAMF7, FASLG, NUGGC and NLRC5." (PMID 32024530, 2020).
melanoma (continued). "Third, our study showed that NLRC5 expression positively correlated with CD8+ T cell infiltration level in multiple melanoma datasets, but did not prove whether NLRC5 affects CD8+ T cell infiltration level in melanoma and its molecular mechanism." (PMID 34307322, 2021). "As NLRC5 could regulate the expression of MHC genes, and its expression correlated with cytotoxicity and infiltrating level of CD8+ T cells in melanoma, we therefore asked whether high NLRC5 expression is associated with good prognosis in patients receiving immunotherapy." (PMID 34307322, 2021). "In addition, we found that NLRC5 expression positively correlated with transcription factor SPI1 expression in 28 kinds of tumor samples from TCGA including TCGA SKCM, which was also consistent with melanoma datasets from the GEO Platform (GSE54467, GSE59455, and GS65904)." (PMID 34307322, 2021). "Among the melanoma patient cohort who received anti-CTLA-4 checkpoint blockade therapy, we observed a reduction in the gene expression level of NLRC5-dependent MHC class I and CD8+ T cell genes in non-responders versus responders." (PMID 33547395, 2021). "However, whether NLRC5 is expressed only in immune cells or not is unclear in melanoma." (PMID 34307322, 2021). "Nlrc5−/− mice exhibit impaired CTL responses, and NLRC5-null target cells are not efficiently cleared by CTLs, while the immunogenic melanoma was able to activate CD8+ T cells by restoring the expression of NLRC5 alongside with CD80." (PMID 34768828, 2021). "Similar to anti-CTLA4-treated patient cohort, NLRC5 and HLA-B was reduced in non-responders, along with a similar trend for B2M in anti-PD1-treated melanoma patients." (PMID 33547395, 2021). "In the Jak-knockout B16 melanoma model, BO-112 appears to upregulate MHC class I (especially HLA-A) in a manner that is dependent on nuclear factor kappa B (NF-κB) and independent of NLRC5." (PMID 38231444, 2024).
viral infection (19 papers, 2013 to 2026). "Indeed, NK-cell-dependent loss of Nlrc5-deficient T cells is observed in CD4cre Nlrc5fl/fl mice following Poly(I:C) pretreatment or viral infection." (PMID 26861112, 2016). "It has been shown that NLRC5 efficiently inhibits viral infection by preventing the activation of RIG-I and MDA5, as well as the generation of type I IFN." (PMID 36146565, 2022). "It is also known that NLRC5 is activated during several viral infections in different cell types including Raus sarcoma virus-infected A549 cells, cytomegalovirus-infected HFF cells and Sendai virus-infected HeLa cells." (PMID 32509599, 2020). "For instance, it has been demonstrated that NLRC5 effectively prevents viral infection by inhibiting the activation of RIG-I and MDA5 as well as the production of type I IFN." (PMID 31824312, 2019). "In the context of virus infection NLRC5 was initially reported to be a positive regulator of type I IFN responses." (PMID 30344524, 2018). "Although the exact biological function of these NLRC5 isoforms has yet to be investigated, our unpublished studies in vivo and in vitro showed the functional difference of zebrafish NLRC5 isoforms in viral infection." (PMID 28714877, 2017). "In spite of this, two independent studies using RNAi, revealed that human NLRC5 positively contributes to type I IFN expression upon viral infection in human cells." (PMID 24319445, 2013). "Agents that induce IFN-I such as virus infection and TLR ligands such as polyinosinic-polycytidylic acid (poly I:C; TLR3), lipopolysaccharide (LPS; TLR4) and CpG oligonucleotides (TLR9) also cause moderate upregulation of NLRC5." (PMID 33671123, 2021). "However, the analysis revealed upregulation of genes involved in immune responses against viral infection, such as Ddx60 (p = 1.2 × 10–24), Dhx58 (p = 8.8 × 10–45) and Nlrc5 (p = 5.4 × 10–45)." (PMID 31620112, 2019). "Besides, NLRC5 is widely expressed in tissues with bacterial and viral infections, and it can also induce expression of inflammasome-related proteins." (PMID 31824312, 2019). "During viral infection, NLR family CARD domain-containing protein 5 (NLRC5) participates in innate immunity through multiple mechanisms." (PMID 41754499, 2026). "The Guarda laboratory showed that NLRC5 is the crucial mediator of IFN-I mediated upregulation of MHC-I in CD4+ and CD8+ T cells during inflammatory conditions and viral infection and this upregulation is crucial to inhibit their killing by NK cells." (PMID 33671123, 2021). "In detail, following viral infection or stimulation by specific ligands, the caspase recruitment domain (CARD) of RIG-I and MDA5 becomes accessible for NLRC5 which competes with MAVS for binding, thus leading to dampened IRF3 activation." (PMID 30344524, 2018). "All these data demonstrate that NLRX1 and NLRC5 can control the type I IFN and pro-inflammatory responses to live virus infection of human DCs as well." (PMID 30344524, 2018). "The rate of infectivity at a MOI of 10 in vitro was similar between cell lines regardless of NLRC5 expression, suggesting that NLRC5 does not interfere with viral infection in this model." (PMID 38235131, 2023). "Within the ‘Innate immunity’ annotation group, most genes upregulated by RNA-seq were also upregulated by Ribo-seq, except for NLRC5, a negative regulator of NFKB and IFN-I signaling, which was 2.2-fold and 6.2-fold induced by viral infection for RNA-seq and Ribo-seq, respectively." (PMID 33806254, 2021). "For example, the siRNA-mediated knockdown of NLRC5 expression in various cell types has shown both enhancement as well as the decrease of interferon (IFN) response, suggesting NLRC5 can act as a positive and negative regulator of IFN response during viral infection." (PMID 32509599, 2020). "Notably, NSP1 does not alter basal expression of NLRC5 or MHC-I under physiological conditions, indicating its exclusive inhibition of de novo NLRC5 mRNA translation during viral infection." (PMID 41156582, 2025).
Obesity (9 papers, 2017 to 2026). Accumulation of substantial excess body fat. "Polymorphisms in NLRC5 are associated with obesity, type 2 diabetes mellitus (T2DM), and MASLD and limit the NF-kB signaling pathway." (PMID 38540416, 2024). "For instance, NLRC5 methylation was associated with BMI and obesity in Africans53 and with HIV infection." (PMID 31900413, 2020). "Transferring these results to humans, genetic variants of NLRC5 leading to diminished NLRC5 functionality could favor the development of obesity." (PMID 37239938, 2023). "Of the 22 human NLRs known to date, six proteins (NLRP3, NLRP6, NOD1, NOD2, NLRC5 and NLRP12) have been described to be associated with obesity and low-grade inflammation and one (NLRP3) with postprandial inflammation." (PMID 37239938, 2023). "The DMPs annotated to genes CPT1A, NLRC5 and BCAT1, which were associated with three out of four anthropometric indices studied, combined attributed to 7.6% of the variance on obesity." (PMID 28947923, 2017). "Based on these data, we can speculate that conditions characterized by reduced NAD+ levels, such as ageing or obesity, might increase NLRC5 levels to influence cellular metabolism or license cell death." (PMID 39035010, 2024). "Moreover, multiple studies described the connection between NLRC5 and metabolic conditions including obesity, but also an interaction of NLRC5 with PPARγ1, a key regulator of lipid metabolism and beyond, fostering the transcriptional activity of the latter." (PMID 39035010, 2024). "The odds for the obesity were 0.85, 1.04 and 0.94 for the DMPs annotated to genes CPT1A, NLRC5 and BCAT1, respectively." (PMID 28947923, 2017). "DMPs cg07839457 and cg20399616, annotated to genes NLRC5 and BCAT1, respectively, were associated with BMI, WC and obesity but not with abdominal obesity." (PMID 28947923, 2017). "DMP cg07839457 located 1.5 kb upstream of the transcription start site (TSS) of NLRC5 was found in our study to be hyper-methylated for higher BMI and WC, and 7.1% hyper-methylated in those with obesity compared with those without." (PMID 28947923, 2017). "DMP cg07839457 (NLRC5) and cg20399616 (BCAT1) were significantly associated with BMI, obesity and with WC and had not been reported by previous EWAS on adiposity." (PMID 28947923, 2017). "Notably, we found three DMPs or loci (CPT1A, NLRC5 and BCAT1) that showed epigenome-wide significance with both obesity and abdominal obesity." (PMID 28947923, 2017). "In contrast, only three DMPs—cg00574958, cg07839457 and cg20399616—, annotated to genes CPT1A, NLRC5 and BCAT1, respectively, were significantly differentially methylated in those with obesity compared with those without." (PMID 28947923, 2017).
rheumatoid arthritis (9 papers, 2019 to 2025). A chronic, systemic autoimmune disorder characterized by inflammation in the synovial membranes and articular surfaces. "NLRC5 is a key regulator of the adaptive immune response stimulating the production of inflammatory cytokines, and its deregulation has also been linked to the pathogenesis of rheumatoid arthritis." (PMID 35796900, 2022). "Similarly, we identified relevant protein associations for cg19693031 (TXNIP gene) previously associated with type 2 diabetes and cg07839457 (NLRC5 gene) previously associated with immune-related proteins such as CD48 antigen or traits such as rheumatoid arthritis." (PMID 41361833, 2025). "Moreover, NLRC5 methylation has been associated with lupus and rheumatoid arthritis." (PMID 34220868, 2021). "Previous studies have revealed that NLRC5 plays a critical role in rheumatoid arthritis has been found to regulate FLS invasion, migration, and inflammation." (PMID 39092772, 2024). "NLRC5 modulates inflammatory responses and plays a role in immune diseases including rheumatoid arthritis, as well as liver, renal, heart, lung, and spleen diseases by regulating the NF-kB, type I interferon, and inflammasome signalling pathways." (PMID 38571307, 2024). "A review of the novel sites using the EWAS Catalog showed previous associations with Crohn’s disease, rheumatoid arthritis, systemic lupus erythematosus, and TNF-α for NLRC5 (Nod-like receptor family CARD domain containing 5; cg16411857)." (PMID 38571307, 2024). "A recent study has shown that NLRC5 expression was increased in synovial tissues of rheumatoid arthritis (RA) rats." (PMID 34438368, 2021). "In contrast, dexmedetomidine suppressed rheumatoid arthritis by downregulating NLRC5 expression." (PMID 39092772, 2024). "Following recent advances, this paper aims to provide a comprehensive update on the diverse pharmacological roles of NLRC5 in the process of immune diseases, especially on liver diseases, renal diseases, rheumatoid arthritis, heart diseases, lung diseases, and spleen diseases." (PMID 31824312, 2019). "In vivo rat model of rheumatoid arthritis (RA), DEX suppresses NLRC5, therefore reducing cytokine levels of IL-1β, IL-6, IL-17A, and TNF-α." (PMID 35628263, 2022).
endometrial cancer (8 papers, 2023 to 2025). Primary or metastatic malignant neoplasm involving the endometrium (mucous membrane that lines the endometrial cavity). "Recently, in an in vitro study in endometrial cancer, Fan and co-workers showed that the upregulation of NLRC5 expression induced cell migration and invasion by activating the PI3K/AKT signaling pathway." (PMID 38961101, 2024). "The innate immune molecule NLR family CARD domain-containing 5 (NLRC5) plays a significant role in endometrial carcinoma (EC) immunosurveillance." (PMID 38822039, 2024). "Interestingly, NLRC5 is down-regulated in endometrial cancer, however, the over-expression of NLRC5 promotes the migration and invasion of endometrial cancer cells." (PMID 38961101, 2024). "In endometrial cancer, NOD-like receptor family CARD do-main-containing 5 (NLRC5) modulates NF-κB to drive progression." (PMID 40361374, 2025). "By contrast, in endometrial cancer, METTL3 safeguards NLRC5 via a YTHDF2-dependent mechanism, maintaining MHC-I transcriptional programs and associating with greater CD8+ T-cell presence and tumor control." (PMID 41280938, 2025). "In endometrial cancer, the autophagy protein LC3 interacts with and inhibits the function of MHC-class-I transactivator NLRC5, represses MHC expression, and promotes escape from antitumor immunity." (PMID 39409895, 2024). "Overexpression of METTL3 promotes m6A modification of NLRC5, increases the proportion of CD8+ T cells, and inhibits the progression of endometrial cancer." (PMID 39726589, 2024).